INS (insulin)
Diseases named in the same sentence as INS in open-access papers (continued):
Sharing a sentence is not in itself a finding about the gene and the disease.
endothelial dysfunction (continued). "For NSAIDs subgroup analyses, the within-group significant associations for the insulin-related and inflammatory/endothelial dysfunction biomarkers were found among non-users and regular users alike." (PMID 34616762, 2021). "Therefore, this study aimed to investigate the aging-related insulin- and IGF-1-mediated endothelial dysfunction and antioxidant deficiency in SHRs." (PMID 34203897, 2021). "Therefore, endothelial dysfunction reduces vasodilation and increases vascular resistance, limiting insulin and glucose delivery in the sensitive tissues (ie, skeletal muscle, liver, and adipose tissue) and blunts insulin-stimulated glucose uptake." (PMID 33926442, 2021). "However, insulin sensitivity or the endothelial dysfunction induced by HFD cannot be improved after returning to a normal diet, suggesting the existence of metabolic memory in the HFD-induced model." (PMID 34327200, 2021). "This imbalance may lead to endothelial dysfunction characteristic of insulin resistant states and may progress to the remodeling of vascular wall and atherosclerotic lesions." (PMID 33117166, 2020). "Linagliptin, a DPP4 inhibitor when added to insulin, metformin or both may improve endothelial dysfunction in a diabetic kidney disease (DKD) population." (PMID 32493344, 2020). "Moreover, treatment with CSAT+® attenuated endothelial dysfunction and increased vascular sensitivity to insulin." (PMID 32326269, 2020). "A well characterized mechanism that leads to systemic endothelial dysfunction in the metabolic syndrome is insulin resistance, since insulin triggers AKT-dependent endothelial nitric oxide synthase (eNOS) phosphorylation, which mediates endothelial NO synthesis and release." (PMID 33198153, 2020). "An open but important question is whether albuminuria, which is often related to autonomous neuropathy and endothelial dysfunction, influences the effect of insulin on blood flow and/or arterial stiffness." (PMID 31119456, 2019). "For example, endothelium-to-mesenchymal transition, high glucose levels, insulin resistance, disturbed blood flow, and oxidative stress in the induction of endothelial dysfunction have been discovered to be crucial mechanisms in mediating the development of pulmonary hypertension." (PMID 31540416, 2019). "Another possible link between hyperuricemia and IR could be hyperuricemia-mediated endothelial dysfunction which may lead to lower insulin uptake by reduced blood flow in peripheral tissues and may worsen the IR." (PMID 30759960, 2019). "Endothelial dysfunction can also diminish insulin’s delivery to the interstitium and could thereby limit insulin action." (PMID 31783601, 2019). "Different factors, such as increased vasodilatory capacity, protection against endothelial dysfunction, increased insulin sensitivity, increased arteriole density and manifest adaptation of stress- and energy-metabolism-related genes have been suggested to explain this beneficial effect." (PMID 28069013, 2017). "It remains to be established whether inhibition of GRK2 in the liver reduces endothelial dysfunction by restoration of glucose homeostasis and insulin sensitivity or vice versa." (PMID 28814745, 2017). "Additionally, in concert with increased VEGF protein expression, insulin stimulates nitric oxide production by the endothelium, and reduced bioavailability of nitric oxide together with oxidative stress results in endothelial dysfunction." (PMID 28836407, 2017). "Free fatty acid-mediated endothelial dysfunction involves several mechanisms including impaired insulin signaling and nitric oxide production, oxidative stress, inflammation and the activation of the renin-angiotensin system and apoptosis in the endothelial cells." (PMID 28750629, 2017). "However, insulin treatment had less potent effects on survival and prevention of cellular senescence and endothelial dysfunction than did TA-1887 treatment." (PMID 28900540, 2017).
endothelial dysfunction (continued). "Lastly, clinical and experimental studies suggest that endothelial dysfunction, likely in the capillary and arteriolar endothelium, which are metabolically involved with insulin-sensitive tissues, is the controlling factor for the amount of insulin that effectively reaches the tissues." (PMID 27013319, 2016). "Ex vivo models of equine vessels incubated in high concentrations of insulin have shown that a similar phenomenon may also occur in horses and this pathophysiological process may contribute to the endothelial dysfunction evident in this study." (PMID 27684374, 2016). "It has been shown that delayed insulin delivery can occur due to endothelial dysfunction." (PMID 27923363, 2016). "The goal of the present study was to analyze the role of PTP1B in the control of endothelial function and to determine whether PTP1B deletion could prevent endothelial dysfunction in situations of diminished insulin secretion." (PMID 25974252, 2015). "We hypothesized that metabolic dysfunctions increase PTP1B expression in endothelial cells and that PTP1B deletion prevents endothelial dysfunction in situation of diminished insulin secretion." (PMID 25974252, 2015). "In addition, cocoa intake improves lipid profile and insulin sensibility, reduces platelet activity and function, and ameliorates endothelial dysfunction." (PMID 26633471, 2015). "One can advance the hypothesis that the large increase in insulin levels observed in our HFD-IH group may contribute to prevent HFD-induced endothelial dysfunction." (PMID 25993257, 2015). "To further determine whether MI-induced endothelial dysfunction may affect the endothelial response to insulin, we further measured the vasorelaxation of arterial rings to insulin." (PMID 25907785, 2015). "Thus, VAS2870-induced effects are consistent with available data in which an improvement of endothelial dysfunction was observed by specifically targeting NADPH oxidase in insulin resistant mice." (PMID 25807378, 2015). "Other mediators, namely adiponectin, could have a protective role in endothelial dysfunction, and may exert an anti-atherogenic effect by vasodilatation, also independently of insulin sensitivity." (PMID 23934358, 2014). "The mechanisms linking arterial stiffness to CVD are not completely understood, and may involve insulin resistance promoting endothelial dysfunction, oxidative stress, vascular smooth muscle cell growth and stimulation of the sympathetic nervous system." (PMID 24559092, 2014). "DHSGT treatment restored decreased PPAR-γ expression levels in the aorta of western diet-fed ApoE KO mice and the beneficial effect of DHSGT on endothelial dysfunction in diabetic atherosclerosis was similar to rosiglitazone (a PPARγ agonist) which is ameliorated in insulin sensitivity." (PMID 25280587, 2014). "CRP may detrimentally affect the vascular wall by reducing nitric oxide bioavailability and inducing endothelial dysfunction, which may impair insulin endocytosis in endothelial cells." (PMID 25105149, 2014). "IR may impair the PI3K-dependent signaling, alter the balance between NO and endothelin-1 towards diminished insulin-induced vasodilation or even vasoconstriction leading to exacerbated IR and endothelial dysfunction." (PMID 24391852, 2013). "At the myocardial level, insulin inhibits NO production; consequently, an insufficient response to the hormone may determine reduced NO release, with potential endothelial dysfunction." (PMID 23590337, 2013). "In this study we wanted to test, whether an antidiabetic treatment with either insulin or metformin can improve endothelial dysfunction and restore vasorelaxation to adiponectin in ZDF rats." (PMID 23497197, 2013). "Insulin could be acting as protecting factor for placental microvascular endothelial dysfunction in GDM." (PMID 22808198, 2012).
endothelial dysfunction (continued). "Some inflammatory mediators originating from the adipose tissue can lead to local insulin resistance with an impaired inhibitory effect of insulin on the release of free fatty acids (FFAs) and endothelial dysfunction, thus assuming a special meaning in promoting early arterial damage." (PMID 22938533, 2012). "The potential mechanisms may be that severe NAFLD may contribute to MACEs by stimulating platelet activation or by aggravating systemic inflammation, liver insulin resistance, macrophage activation, increased oxidative stress, endothelial dysfunction, and altered lipid metabolism." (PMID 38773388, 2024). "Endothelial dysfunction is another mechanism hypothesizing that long-term exposure to air pollution affects endothelial function in humans and animals, resulting in decreased insulin sensitivity, as well as reduced peripheral blood glucose uptake." (PMID 39590972, 2024). "Furthermore, oxidative stress may elicit profibrotic and proinflammatory pathways, which alter endothelial dysfunction and insulin metabolic signaling by promoting renal and cardiovascular fibrosis." (PMID 38539304, 2024). "Mechanisms of this association include activation of the renin-angiotensin-aldosterone system by increasing sympathetic activity, insulin resistance, leptin resistance, increased procoagulant activity, and endothelial dysfunction, which may lead to HTN and cardiovascular disease." (PMID 38566160, 2024). "Additionally, studies have shown that pyridoxine may improve insulin signaling and prevent endothelial dysfunction and intrahepatic fat accumulation." (PMID 36147306, 2022). "In insulin-resistant conditions, impairment of the PI3K-dependent signaling may cause imbalance between production of NO and secretion of endothelin-1 and lead to endothelial dysfunction." (PMID 33925119, 2021). "The changes observed overtime after sunitinib treatment in terms of markers of early endothelial dysfunction, blood pressure, as well as in glucose/insulin metabolism and proteinuria may contribute to increase CV risk in RCC patients and suggest a strict follow‐up in this setting." (PMID 32270594, 2020). "In conclusion, the modifications observed overtime after sunitinib treatment in terms of markers of early endothelial dysfunction, blood pressure, as well as in glucose/insulin metabolism and proteinuria might increase the cardiovascular risk in RCC patients treated with sunitinib." (PMID 32270594, 2020). "Higher compliance to the dietary pattern which is similar to the DASH diet could mediate decreased risk of CKD by modifying several cardio-metabolic risk factors, e.g. improved plasma lipid profiles, blood pressure, insulin sensitivity, oxidative stress, inflammation, and endothelial dysfunction." (PMID 30564279, 2018). "During insulin-resistant conditions, pathway-specific impairment in PI3K-dependent signaling may cause imbalance between production of nitric oxide (NO) and secretion of endothelin-1 and lead to endothelial dysfunction." (PMID 29588341, 2018). "Previous studies show that the mechanisms of palmitic acid induced cell damages mainly involve insulin resistance, endoplasmic reticulum stress (ERS), oxidative stress, apoptosis, autophagy, and production of many pro-inflammatory factors to cause endothelial dysfunction and cardiovascular diseases." (PMID 27043548, 2016). "However, whether deletion of PTP1B represents a protective mechanism against endothelial dysfunction in situations of diminished insulin secretion remains unknown." (PMID 25974252, 2015). "Another effect of oxidative stress-mediating endothelial dysfunction might rely on the deleterious effects of ROS on insulin signaling by activating stress-sensitive pathways including JNK, p38 MAPK, IKKβ kinases, and nuclear factor-kappaB in endothelial cells." (PMID 25143800, 2014).
endothelial dysfunction (continued). "The isolated decrease in SBP found in this study may hypothetically be related to increased insulin sensitivity and increased vascular resistance, mediated by a disease-related inotropic effect that may result in endothelial dysfunction and an increased vascular resistance." (PMID 24026893, 2013). "This is relevant because insulin-mediated glucose uptake as well as the reactivity of vessels in insulin-sensitive tissues are modulated by NO generated in the endothelium; thus, IR represents an important pathogenetic mechanism in the development of endothelial dysfunction and T2D." (PMID 23203035, 2012). "Therefore, endothelial dysfunction is hypothesised to be a primary step in the development of the insulin resistant state." (PMID 21959060, 2011). "Endothelial dysfunction can be promoted by leptin, FT4, insulin and CRP while adiponectin improves endothelial dysfunction by inducing the production of nitric oxide." (PMID 36520252, 2023). "Possible pathways proposed to explain the mechanism include endothelial dysfunction, blood-brain barrier (BBB) dysfunction, oxidative stress or inflammation due to failure of cells to respond to insulin in the brain." (PMID 35992100, 2022). "Adipose tissue inflammation, oxidative stress, endothelial dysfunction, and DNA methylation can be also induced by PM2.5, which further results in endoplasmic reticulum stress, insulin signaling abnormalities, and apoptosis." (PMID 35317761, 2022). "This study demonstrated that the process of aging additively affected insulin- and IGF-1-mediated endothelial dysfunction mainly through impairing the PI3K-NOS-NO pathway in SHRs." (PMID 34203897, 2021). "On the one hand, an impaired insulin signal via PI3K-Akt directly reduces endothelial NO synthase (eNOS) activation, leading to endothelial dysfunction." (PMID 32194402, 2020). "By attenuating insulin signaling and thus preventing insulin-mediated vascular effects, PTP1B has been found to play a major role in endothelial dysfunction and cardiovascular disorders." (PMID 31319588, 2019). "Several mechanisms of endothelial dysfunction in T2DM have been identified, including alterations in insulin signaling." (PMID 29425121, 2018). "What is more, when the balance in insulin resistance is shifted towards the MAPK/ERK pathway, it results in a release of inflammatory markers by insulin (e.g., PAI-1, ICAM-1, VCAM-1, and E-selectin) and finally promotes the endothelial dysfunction." (PMID 27413253, 2016). "Taken together, these results suggest that SIRT3 is a positive regulator in endothelial insulin sensitivity and a protector against HFD-induced endothelial dysfunction." (PMID 27000941, 2016). "Collectively, all these data indicated that mtROS is involved in the regulation of SIRT3 on endothelial insulin sensitivity and SIRT3 protects against HFD-induced endothelial dysfunction by inhibiting mtROS increase." (PMID 27000941, 2016). "Genes indicated by 16 shared risk loci point to mechanisms with potential roles in migraine pathogenesis and CAD, including endothelial dysfunction (PHACTR1) and insulin homeostasis (GIP)." (PMID 27066539, 2015). "Second, while the role of PKC in endothelial dysfunction is well documented, less is known about smooth muscle cell (SMC) response to insulin." (PMID 21635764, 2011). "Shared mechanisms include visceral adiposity, adipokine imbalance, insulin resistance, systemic cytokine activation (IL-6, TNF-α), endothelial dysfunction, oxidative stress, intermittent hypoxia, and profibrotic transforming growth factor-beta (TGF-β)–mediated pathways." (PMID 41995935, 2026). "CTE supplementation, alone or in combination with BPL1® HT, prevented MetS-induced endothelial dysfunction (p < 0.05), whereas supplementation with BPL1® HT alone did not have any impact either in the vascular response to Ach or the vascular response to insulin." (PMID 41596333, 2026).
endothelial dysfunction (continued). "In summary, insulin-stimulated muscle glucose uptake is enhanced in Cd36−/− mice independent of microvascular adaptations that improve insulin delivery and despite presence of endothelial dysfunction." (PMID 39503770, 2025). "Increased serum FGF21 may compensate for endothelial dysfunction in retinopathy, with defects in FGF21 expression or activation reducing insulin sensitivity, liver fatty acid oxidation, and triglyceride clearance." (PMID 39687000, 2024). "Chronic CAP exposure is known to induce vascular dysfunction, but we used an acute exposure protocol (9‐day) that is known to stimulate early changes in vascular signaling (insulin and VEGF resistance) and inflammation that portend endothelial dysfunction and favor pro‐atherosclerotic changes." (PMID 34755498, 2021). "Under diabetic conditions, insulin signaling is impaired at the level of IRS-1, leading to decreased glucose transport and metabolism, impaired endothelial nitric oxide synthase (eNOS) activation and endothelial dysfunction." (PMID 33937238, 2021). "It is unclear why in the endothelial dysfunction did not occur, but we were able to examine the effect of ucOC following acute high glucose incubations and in an insulin‐resistant state following the atherogenic diet." (PMID 32936958, 2021). "Under insulin-resistant conditions where the pathway-specific impairment in PI3K-dependent signaling occurs, the imbalance between NO and ET-1 may result in endothelial dysfunction with subsequent cardiovascular events." (PMID 33708129, 2021). "This study demonstrated that the process of aging additively affected insulin- and IGF-1-mediated endothelial dysfunction in SHRs, which could be partly attributed to the reduced NO production and antioxidant deficiency." (PMID 34203897, 2021). "For example, a recent study identified that 1 week of daily consumption of a glucose sweetened beverage‐induced conduit artery endothelial dysfunction independent of changes in fasting glucose or insulin concentrations." (PMID 34676680, 2021). "Acacetin is dependent on estrogen-like action to reduce the levels of inflammatory factors, inhibit ERK pathway, down-regulate ARG2 and increase NO to relax the blood vessels, so as to alleviate endothelial dysfunction and improve the aortic fibrosis of SHR rats with insulin-resistant." (PMID 32892299, 2020). "In the absence of estrogen, endothelial dysfunction leads to a change in permeability, reducing peripheral blood flow and, consequently, impairing the action of insulin." (PMID 30192778, 2018). "On the other hand, various nondiabetic drugs seem to play a crucial role in insulin sensitivity and endothelial dysfunction." (PMID 30425742, 2018). "To examine whether ER stress is involved in endothelial dysfunction induced by SLE plasma we measured NO production induced by the calcium ionophore A23187 and insulin in HUVECs incubated with 4-PBA." (PMID 29208022, 2017). "We sought to determine whether hepatic GRK2 siRNA transfection would improve endothelial dysfunction via GRK2 regulation of glucose metabolism and insulin sensitivity." (PMID 28814745, 2017). "In summary, we found that biomarkers of endothelial dysfunction are related to impaired insulin sensitivity and moreover notably increased in females with recent history of GDM." (PMID 25281032, 2014). "However, neither overexpression nor knockdown of IRSp53 affected the protective role of insulin in endothelial dysfunction." (PMID 33506012, 2021). "Altogether, our results demonstrate that for non-obese Panx1-400C subjects, elevation in triglyceride and insulin concentrations as well as increased HOMA promote endothelial dysfunction and a reduction in MFR, effects that are absent or even slightly inverted in non-obese Panx1-400A subjects." (PMID 32023876, 2020).